DKK3 (dickkopf Wnt signaling pathway inhibitor 3)
Diseases named in the same sentence as DKK3 in open-access papers (continued):
Sharing a sentence is not in itself a finding about the gene and the disease.
ischemic stroke (3 papers, 2020 to 2024). A stroke disorder caused by obstruction of blood flow to the brain, due to thrombotic (local blood clot formation) or embolic (due to a blood clot or other material traveling from another site) event. "Such methodological advantages enable us to draw more accurate conclusions for the association between serum Dkk-3 and clinical outcomes after ischemic stroke." (PMID 31918729, 2020). "This study aimed to investigate the association between serum Dkk-3 and the prognosis of ischemic stroke." (PMID 31918729, 2020). "In this large-sample multicenter study of ischemic stroke patients, we found a U-shaped association between serum Dkk-3 and the risk of death and vascular events after adjustment for potential confounders." (PMID 31918729, 2020). "The aim of this study was to investigate the association of serum Dkk-3 levels with prognosis in patients with ischemic stroke using data from the CATIS (China Antihypertensive Trial in Acute Ischemic Stroke)." (PMID 31918729, 2020). "First, this study is not a specially designed study for the association between serum Dkk-3 and prognosis of ischemic stroke, but an observational study based on the participants from CATIS." (PMID 31918729, 2020). "From findings of this study, serum Dkk-3 might be useful in the risk stratification of prognosis of ischemic stroke and could assist the selection of high-risk patients for aggressive monitoring and therapeutic interventions." (PMID 31918729, 2020). "Several biological mechanisms may underlie the observed U-shaped association of serum Dkk-3 with death and vascular events after ischemic stroke." (PMID 31918729, 2020). "Both low and high serum Dkk-3 levels are associated with increased risks of death and vascular events within 3 months after ischemic stroke, indicating that serum Dkk-3 may have a special effect on the prognosis of ischemic stroke." (PMID 31918729, 2020). "Therefore, it is hypothesized that decreased DKK3 levels in patients after ischemic stroke may be a risk factor for poor prognosis, and therefore detection of DKK3 levels at admission can predict the adverse outcomes in patients." (PMID 38678874, 2024). "Both low and high serum Dkk-3 levels are associated with death and vascular events within 3 months after ischemic stroke, with minimum risk observed in the third quintile of serum Dkk-3, indicating that serum Dkk-3 may have a special effect on the prognosis of ischemic stroke." (PMID 31918729, 2020). "Moreover, the addition of serum Dkk-3 to conventional prognostic factors could significantly improve the risk prediction for death and vascular events after ischemic stroke, as evidenced by NRI and IDI." (PMID 31918729, 2020). "We examined whether adding serum Dkk-3 to a Cox proportional hazards regression model consisting of conventional risk factors improved the risk prediction of adverse clinical outcomes after ischemic stroke." (PMID 31918729, 2020). "During 3 months of follow-up, the cumulative incidence rates of primary outcome among ischemic stroke patients in five quintiles of serum Dkk-3 (from low to high) were 4.49%, 3.74%, 2.54%, 5.23%, and 6.73%, respectively (log-rank p = 0.004)." (PMID 31918729, 2020). "The present study provided valuable evidence for the important role of serum Dkk-3 in the pathogenesis of ischemic stroke." (PMID 31918729, 2020). "Our study has important clinical implications for better understanding the effects of Dkk-3 in pathological process after ischemic stroke onset." (PMID 31918729, 2020). "Further studies from other samples of ischemic stroke patients are needed to validate the effects or prognostic value of serum Dkk-3 after ischemic stroke." (PMID 31918729, 2020). "We measured serum Dkk-3 levels in 3344 ischemic stroke patients from CATIS (China Antihypertensive Trial in Acute Ischemic Stroke)." (PMID 31918729, 2020).
ischemic stroke (continued). "Similarly, the lowest cumulative incidence rates of death (log-rank p = 0.002) and vascular events (log-rank p = 0.033) within 3 months after ischemic stroke were also observed among patients in the third quintile of serum Dkk-3." (PMID 31918729, 2020). "Second, we did not conduct serial measurements of serum Dkk-3 levels after ischemic stroke onset, so we were unable to examine the association between changes of serum Dkk-3 and prognosis of ischemic stroke." (PMID 31918729, 2020). "The study CATIS, a large-sample multicentric trial, demonstrated worse clinical outcomes in patients affected by an ischemic stroke, whether in the presence of high levels either of low levels of DKK-3." (PMID 33317034, 2020). "In view of these biological mechanisms, both low and high serum Dkk-3 levels might induce increased risks of death and vascular events after ischemic stroke." (PMID 31918729, 2020). "We also found that serum Dkk-3 might be a prognostic biomarker for ischemic stroke." (PMID 31918729, 2020). "However, the relationship between serum Dkk-3 and prognosis of ischemic stroke has not yet been studied." (PMID 31918729, 2020).
lung adenocarcinoma (3 papers, 2014 to 2025). A carcinoma that arises from the lung and is characterized by the presence of malignant glandular epithelial cells. "Furthermore, DKK3 may induce cell cycle arrest and apoptosis via the Wnt/β‐catenin pathway, and reduce cell proliferation and invasiveness in lung adenocarcinoma." (PMID 40753072, 2025).
lymph node metastasis (3 papers, 2010 to 2022). "DKK3 methylation was found to be associated with some clinicopathological features such as clinical stage, lymph node metastasis and ER status." (PMID 23890219, 2013). "The results from Chi-squared test showed that the expression level of DKK3 was significantly associated with FIGO stage (p = 0.011) and lymph node metastasis (p = 0.014)." (PMID 35924156, 2022). "Moreover, DKK3 was correlated with FIGO stage and lymph node metastasis." (PMID 35924156, 2022).
Obesity (3 papers, 2023 to 2025). Accumulation of substantial excess body fat. "A recent study shed light on transcriptional regulation of myofiber-derived Dkk3, a secreted protein involved in muscle differentiation, which has therapeutic implications in damage-induced muscle regeneration and obesity-associated muscle atrophy." (PMID 39872244, 2023). "AAV-shRNA knockdown of Dkk3 improved obesity-associated muscle regeneration defect in mice, suggesting that it is a potential drug target for treating obesity-associated muscle weakness." (PMID 39872244, 2023). "Muscle Baf60c gene expression negatively correlates with obesity from the investigators’ previous study, in line with their new data demonstrating a positive correlation between Dkk3 RNA and protein levels with obesity in human muscle and plasma samples as well as muscle samples from mouse models." (PMID 39872244, 2023).
oral squamous cell carcinoma (3 papers, 2020 to 2025). "Moreover, knockdown of Dkk-3 inhibited cell migration and invasion in oral squamous cell carcinoma, possibly contributing to the activation of Wnt signalling pathways." (PMID 32284738, 2020). "In contrast, in some other cancers such as oral squamous cell carcinoma (OSCC) and ganglioneuroma, the DKK3 promoter is not hypermethylated and these cancers express high levels of Dkk-3." (PMID 36497305, 2022).
prostate adenocarcinoma (3 papers, 2010 to 2023). "Adenoviral vector encoding REIC/Dkk-3 gene suppressed the cell growth of human prostate adenocarcinoma LNCaP cells in vitro by inhibiting CD147 expression." (PMID 30257488, 2018). "Additional reports showed consistent reduction of DKK3 expression in prostate adenocarcinomas, particularly those with a high Gleason grade." (PMID 20976069, 2010). "Our results showed amplification of the DKK3 gene in 4% of prostate adenocarcinoma patients." (PMID 36845147, 2023).
schizophrenia (3 papers, 2013 to 2026). A major psychotic disorder characterized by abnormalities in the perception or expression of reality. "Gene expression analysis of the Wnt signalling antagonist Dickkopf-3 (Dkk3) has shown that its mRNA is down regulated in the temporal cortex of elderly people with schizophrenia." (PMID 24403877, 2013). "This work offers novel insight into the shared molecular basis of antipsychotic response and side effects and suggests DKK3 as a promising biomarker for personalized treatment strategies in schizophrenia informed by germline regulatory variation and potential germline alteration." (PMID 42317215, 2026).
Stroke (3 papers, 2020 to 2024). Sudden impairment of blood flow to a part of the brain due to occlusion or rupture of an artery to the brain. "DKK3 is an emerging target in the field of stroke, and DKK3 is thought to be potentially neurotoxic in cerebral ischemia as an inhibitor of Wnt/β-catenin signaling." (PMID 38362904, 2024). "Ang-2 and DKK3 were selected by backward selection to be included as explanatory variables of post-stroke AF." (PMID 35859587, 2022).
systemic lupus erythematosus (3 papers, 2021 to 2023). An autoimmune multi-organ disease typically associated with vasculopathy and autoantibody production. "We need more studies to advance our understanding of the role of DKK3 in autoimmune diseases, including systemic lupus erythematosus (SLE)." (PMID 35683365, 2022). "Here, we investigated the prognostic role of DKK3 in systemic lupus erythematosus (SLE) patients with and without LN, assessing its changes in relation to kidney function, flares, and interstitial fibrosis." (PMID 35683365, 2022).
adenovirus infection (2 papers, 2014 to 2020). "However, a separate study has reported that Dkk3-carrying adenovirus infection of normal human fibroblasts induced interleukin-7 production, triggered by ER stress proteins (ASK1, p38, IRE1α and IRF-1)." (PMID 33425757, 2020).
adrenocortical carcinoma (2 papers, 2017 to 2023). "While robust expression was observed in normal adrenal cortex, DKK3 was down-regulated in the majority (>75%) of adrenocortical carcinomas (ACC) tested." (PMID 28249601, 2017). "DKK3 is weakly expressed in most adrenocortical carcinoma tumor tissues, suggesting a possible oncogenic role in ACC." (PMID 38269250, 2023). "We analyzed the expression and regulation of DKK3 in human adrenocortical carcinoma (ACC) by qRT-PCR, immunofluorescence, promoter methylation assay, and copy number analysis." (PMID 28249601, 2017).
aortic aneurysm (2 papers, 2024 to 2025). A ruptured aneurysm located in the wall of the proximal portion of the descending aorta proceeding from the arch of the aorta. "In our study, single-cell RNA-sequencing data analysis demonstrated a substantial elevation in modulated VSMCs in patients with aortic aneurysm, accompanied by Dickkopf 3 (DKK3) up-regulation." (PMID 40948935, 2025).
asthma (2 papers, 2020 to 2021). "Asthmatic patients with Wnt regulator (WIF1, WNT5B, and DKK3) enrichment were atopic, had early-onset, long duration, and had severe asthma with the inflammatory profile." (PMID 33791298, 2021). "We aimed to analyze the diagnostic properties of plasma Dkk-3, CAF22 and selected miRs to evaluate skeletal muscle detriment in COPD, asthma and pulmonary TB." (PMID 33023021, 2020). "In general, plasma DKK-3 levels showed a stronger association with HGS in COPD and asthma, while CAF22 levels had the strongest association with HGS in pulmonary TB." (PMID 33023021, 2020). "Plasma Dkk-3 and CAF22 levels were higher in patients with COPD (≈24% and ≈93%, respectively, p < 0.05) and asthma (≈17% and ≈70%, respectively, p < 0.05), while the plasma CAF22 levels were elevated in patients with pulmonary TB (≈42%, p < 0.05) compared to healthy controls." (PMID 33023021, 2020).
Autoimmunity (2 papers, 2015 to 2022). The occurrence of an immune reaction against the organism's own cells or tissues. "Our findings provide strong evidence that Dkk3 contributes to the immunoregulatory properties of the tissue microenvironment and therefore may provide a valuable target for immune intervention in autoimmunity, transplantation, and inflammatory disease." (PMID 25759692, 2015). "The locally restricted function might also explain, at least in part, why Dkk3 deficiency does not lead to T-cell activation in secondary lymphoid organs in the steady state and thus, why Dkk3−/− mice do not suffer from spontaneous autoimmunity." (PMID 25759692, 2015). "It is currently not clear whether the FoxO4/DKK3 axis in T cells is required during autoimmunity or other infectious diseases, which warrants further investigation." (PMID 36106640, 2022).
B acute lymphoblastic leukemia (2 papers, 2017 to 2023). "This is further supported by epigenetic influence through high expression of micro-RNA impacting Wnt/β-catenin inhibitor (DKK3) as reported in adult B-cell lymphoblastic leukemia." (PMID 36661526, 2023).
brain ischemia (2 papers, 2018 to 2024). Diminished or absent blood supply to the brain caused by obstruction (thrombosis or embolism) of an artery resulting in neurologic damage. "In a model of focal brain ischemia induced by permanent middle cerebral artery (MCA) occlusion (MCAO) Dkk3−/− mice showed a significantly greater infarct size with respect to their wild-type counterparts at all time points investigated (1, 3 and 7 days after MCAO)." (PMID 30258353, 2018).
chronic pancreatitis (2 papers, 2021 to 2026). A chronic inflammatory process causing damage and fibrosis of the pancreatic parenchyma. "We have previously identified DKK3 as a barrier to multiorgan regeneration, including recovery from experimental pancreatitis, and as a biomarker in patients following pancreatic injuries, such as acute and chronic pancreatitis." (PMID 41147409, 2026). "Similarly, DKK3 expression was elevated in pancreata of mice with either caerulein‐induced acute or chronic pancreatitis (AP, CP)." (PMID 34306986, 2021).
colorectal adenoma (2 papers, 2020 to 2022). An adenoma that arises from the colon or rectum. "Herein, we have shown that colorectal adenoma occurred in chemical-exposed and Dkk3-deleted intestine, suggesting that Dkk3 abrogation might enhance chemically induced colorectal carcinogenesis." (PMID 33425757, 2020).
coronary artery disease (2 papers, 2020 to 2025). "This shared inflammatory axis suggests a mechanistic link between periodontitis and cardiovascular disease, highlighting the importance of DKK-3 as one of the significant markers for coronary artery disease (CAD) and periodontitis." (PMID 41356214, 2025).
coronary stenosis (2 papers, 2021 to 2024). Narrowing of the coronary artery lumen diameter. "Serum DKK3 level was also inversely associated with coronary stenosis in a Chinese cohort." (PMID 34631806, 2021).
diabetic nephropathy (2 papers, 2025). "WTAP regulates the m6A modification of DKK3, thereby promoting cell proliferation and migration in diabetic nephropathy." (PMID 39945887, 2025).
keloid (2 papers, 2018 to 2021). An irregularly shaped, elevated mark on the skin caused by deposits of excessive amounts of collagen during wound healing. "DKK3 encodes DickKopf3 and overexpression of this protein in keloid fibroblasts has been shown to suppress cell proliferation and promote apoptosis via TGF-β1/SMAD signaling as well as impairing tumor growth by promoting IL-7 production." (PMID 34539648, 2021). "What’s more, DKK3 overexpression suppressed collagen synthesis, induced cell apoptosis, and inhibited cell proliferation via TGF-β1/smad pathway in keloid fibroblasts." (PMID 30559605, 2018).
kidney cancer (2 papers, 2009 to 2020). Primary or metastatic malignant neoplasm involving the kidney. "Exogenous Dkk3 inhibited Wnt/β-catenin signaling and cell proliferation in kidney cancer cells, and the cysteine-rich core domain of Dkk3 was required for dendritic cell–like differentiation from monocytes and for tumor regression, where it activated phosphorylation of GSK-3β and stat." (PMID 33425757, 2020).
meningioma (2 papers, 2017 to 2018). A generally slow growing tumor attached to the dura mater. "The aim of our study is to demonstrate the role of Dkk-3 and claudin-5 in the pathogenesis of meningiomas." (PMID 28978116, 2017). "At western blot analysis, the data have shown a significantly reduction of Dkk-3 and claudin-5 expression in the meningioma tissue compared with control tissues." (PMID 28978116, 2017). "Actually, our immunohistochemical analysis, showed reduced positivity of Dkk-3 in meningiomas of grade I, even more accentuated in meningiomas grade II." (PMID 28978116, 2017). "Dkk-3 immuno-expression was also found in the nuclei of the endothelial cells of some vessels in all meningiomas." (PMID 28978116, 2017). "In this study, for the first time, we have evaluated the expression of Dkk-3 and claudin-5 in a series of meningiomas." (PMID 28978116, 2017). "By molecular analysis, our findings suggest a key role of Dkk-3 protein in meningiomas, as a potential tumor suppressor, evidenced by its reduced expression in tumor tissues." (PMID 28978116, 2017). "Our result showed an upregulation of both proteins in meningiomas patient compared to control group suggesting that Dkk-3 could have a pro-apoptotic function also in meningiomas." (PMID 28978116, 2017). "In addition, while all grade I meningiomas had both cytoplasmic and nuclear staining for Dkk-3, grade II tumors had only cytoplasmic staining for this protein." (PMID 28978116, 2017). "Our findings suggest that Dkk-3 and claudin-5 could be considered as potential targets for therapeutic approaches in the treatment of meningiomas." (PMID 28978116, 2017). "Interestingly here we observed that DKK3 was mainly overexpressed in aggressive meningiomas." (PMID 29662628, 2018). "Moreover, it has been shown that Dkk-3 is able to modulate apoptosis in many tumorigenesis process such as in ovaric cancer; our work clearly demonstrated that Dkk-3 in meningiomas had pro-apoptotic effects up-regulating both intrinsic and extrinsic apoptotic pathways." (PMID 28978116, 2017). "The purpose of this study was to evaluate the expression of Dkk-3 and claudin-5 in a series of 30 WHO grade I and grade II meningiomas." (PMID 28978116, 2017). "Nowadays, no study has evaluated the expression of Dkk-3 and claudin-5 in meningiomas." (PMID 28978116, 2017).
Myocardial fibrosis (2 papers, 2022 to 2025). "Our previous study found that dickkopf-3 (DKK3) overexpression adequately alleviated Ang II-induced myocardial fibrosis in mice through ADAM17/ACE2 pathway." (PMID 36313337, 2022).
oropharyngeal carcinoma (2 papers, 2015 to 2025). Carcinoma, predominantly squamous cell, arising from the epithelial cells of the oropharynx. "In this regard, frequent hypermethylation of the negative regulators of this pathway (DKK-3, RUNX3, SFRP1, SFRP2, SFRP4, SFRP5, and WIF1) was observed in oral and oropharyngeal cancers." (PMID 25487617, 2015).
oropharyngeal squamous cell carcinoma (2 papers, 2023 to 2025). "This proof-of-concept study suggests that HSI offers the potential for more objective quantification of DKK-3 expression in oropharyngeal squamous cell carcinoma, particularly in cases with weak staining." (PMID 41007216, 2025). "Finally, our team has recently shown that DKK-3 expression is regulated by ΔNp63α in human papillomavirus-positive oropharyngeal squamous cell carcinoma, and that secreted DKK-3 activates NF-κB signaling in macrophages through a CKAP4–Akt–NF–κB axis, without impacting Wnt signaling." (PMID 38201279, 2023).
pancreatic adenocarcinoma (2 papers, 2013 to 2014). "When PAX6 was knocked down by stably transfected PAX6 shRNA in pancreatic adenocarcinoma HPAFII cells, a 4-fold decrease in Dkk3/REIC gene expression was observed." (PMID 25029272, 2014).